MALAT1 (metastasis associated lung adenocarcinoma transcript 1)
Diseases named in the same sentence as MALAT1 in open-access papers (continued):
Sharing a sentence is not in itself a finding about the gene and the disease.
adenocarcinoma (19 papers, 2013 to 2025). A common cancer characterized by the presence of malignant glandular cells. "In basal conditions, TDP-43 is bound by the long-non-coding RNA (lncRNA) Malat1 (metastasis-associated lung adenocarcinoma transcript-1), in humans called MALAT1." (PMID 38693436, 2024). "Processing from longer precursors is not unusual in lncRNAs, since it is already observed in the case of MALAT1 (Metastasis-associated lung adenocarcinoma transcript 1) and NEAT1 (Nuclear enriched abundant transcript 1)." (PMID 34461828, 2021). "This reporter harbors a 95-nt internal poly(A) stretch followed by the 3′-terminal region of the metastasis associated lung adenocarcinoma transcript 1 (MALAT1) noncoding RNA, which is processed by RNaseP and thus lacks a poly(A) tail." (PMID 31570513, 2019). "Here, we used transcriptomic and bioinformatics to analysis LncRNA expression profile during autophagy and functional studies to evaluate the function of the metastasis-associated lung adenocarcinoma transcript-1 (Malat1) lncRNA in macrophages." (PMID 31425535, 2019). "This controversial result may be due to the different mechanisms of MALAT1 involvement in adenocarcinoma and SCC." (PMID 37526759, 2023). "Especially, MALAT1 high RNA level was related to adenocarcinoma, stage 1 and stage 2 (except for OS), stage T1, but not stage 3 or stage T2, stage 3, and stage 4." (PMID 34308750, 2021).
neurodegenerative disease (13 papers, 2016 to 2025). A disorder of the central nervous system characterized by gradual and progressive loss of neural tissue and neurologic function. "Among the abundant lncRNAs that were upregulated by exposing the cells to Sin1 were those implicated in redox homeostasis, energy metabolism, and neurodegenerative diseases (e.g., MALAT1, MIAT, GABPB1-AS1, NEAT1, MIAT, GABPB1-AS1, and HAND2-AS1)." (PMID 36412908, 2022). "MALAT1 was originally reported to be associated with cancerogenesis; however, MALAT1 also plays an important role in neuronal systems, where it has apoptotic and stress response functions, and in neurodegenerative diseases." (PMID 33192306, 2020). "CD14 + MALAT1 + monocyte DEGs were enriched in mitochondrial ATP synthesis-coupled electron transport and some neurodegenerative disease-related pathways." (PMID 37041166, 2023). "Many of these regulatory lncRNAs, such as MALAT1, NEAT1, HOTAIR, etc., are associated with different neurodegenerative diseases in humans." (PMID 36675966, 2022). "Altering levels of MALAT1 affects brain development as well as neuronal function and maintenance in neurodegenerative diseases." (PMID 31422384, 2019). "In human brains from subjects with fronto-temporal lobar degeneration having TDP-43 inclusions (FTLD-TDP), binding of MALAT1 to TDP43 increased, thus suggesting a link between MALAT1 and neurodegenerative diseases." (PMID 29739426, 2018). "Increased interaction of TDP-43 and MALAT1, as well as dysregulation of TDP-43 function, was previously identified in brain samples from patients with neurodegenerative disease compared to healthy brain tissues." (PMID 39837396, 2025). "Dysregulated lncRNAs upon WS treatment included BACE1-AS, MALAT1, SNHG1, HOTAIR, MEG3, BDNF-AS, and SHANK2-AS1 which are potential biomarkers in several neurodegenerative diseases." (PMID 40928594, 2025).
heart disease (11 papers, 2014 to 2024). "lncRNAs, such as APF, CAIF, and MALAT1 (metastasis-associated lung adenocarcinoma transcript 1) were reported to regulate cardiomyocyte apoptosis and autophagy in heart disease." (PMID 32380417, 2020). "Many long non-coding RNAs (lncRNAs), including lncRNA metastasis-associated lung adenocarcinoma transcript 1 (MALAT1), are involved in various cardiac diseases." (PMID 29559566, 2018). "Considering the imperative function of MALAT1 in heart disease and the general role of SNPs, we performed a case–control study in Chinese children to identify and quantitate the association between MALAT1 polymorphism and CHD." (PMID 29559566, 2018). "In heart diseases, MALAT1 regulates cardiomyocyte and endothelial cell proliferation, both are crucial for CHD onset." (PMID 29559566, 2018). "Among them, lncRNA MALAT1 plays an important role in cardiac diseases." (PMID 34745428, 2021). "The lncRNA databases also recommend other heart disease-related lncRNAs, which were differentially expressed in particular ANT-treated conditions, including MALAT1, MEG3, TUG1, GAS5, CASC1S." (PMID 35415316, 2022). "Another study emphasized the important function of other lncRNAs such as H19, MALAT1, and MDNCR at different stages of human cardiac development and heart disease, which inform the lncRNAs’ abilities becoming potential biomarkers as well as therapeutic targets in heart diseases." (PMID 35415316, 2022).
neurological disorders (11 papers, 2020 to 2025). "Except MALAT1, a risk gene of multiple kinds of tumors, there is evidence showing the associations between the other genes and ASD or other neurological diseases." (PMID 33920310, 2021). "Considering the potential neuroprotective function and anti-inflammatory effect of lnc-MALAT1 on different neurological diseases, previous studies examined whether lnc-MALAT1 might have a protective role in the pathology of AD." (PMID 36947499, 2023).
kidney disease (10 papers, 2020 to 2025). "LncRNAs (including plasmacytoma variant translocation 1 [PVT1], and metastasis-associated lung adenocarcinoma transcript 1 [MALAT1]) are associated with the progression of kidney disease." (PMID 38542060, 2024). "Metastasis-associated lung adenocarcinoma transcript 1 (MALAT1) is one of the most comprehensively studied lncRNAs in kidney diseases." (PMID 32295041, 2020). "Further investigation is needed to identify the common pathogenic mechanism for MALAT1 in kidney diseases." (PMID 32295041, 2020). "With respect to kidney disease, circulating levels of MALAT1 are elevated in patients with AKI compared to healthy controls." (PMID 37814337, 2023). "Following this, our in vitro studies indicate that activated ECs secrete more EV-carried MALAT1, suggesting that this may indeed be the reason for the higher circulating MALAT1 levels as observed in patients with kidney disease." (PMID 40978530, 2025). "To demonstrate relevance for humans, we aimed to determine whether MALAT1 dysregulation is consistent in human vascular and fibrotic kidney disease." (PMID 40978530, 2025). "Hypoxia-exposed (1% O2) human-kidney 2 (HK-2) cells promote production of inflammatory cytokines and induce cellular apoptosis, which are both reduced in MALAT1 knockdown experiments, suggesting that MALAT1 may have a molecular role in kidney disease." (PMID 37814337, 2023). "In addition, it is noteworthy that by analyzing lncRNA studies performed on renal diseases, we can identify six lncRNAs involved in more than one type of renal disease, in particular PVT1, TUG1, NEAT1, MALAT1, XIST, and H19." (PMID 37190024, 2023). "There were no published studies about MALAT1 in kidney diseases so far." (PMID 33936064, 2021).
metabolic disorders (10 papers, 2018 to 2026). "Recently, there has been tremendous focus on the possible role of metastasis-associated lung adenocarcinoma transcript 1 (MALAT1) in the pathogenesis of metabolic disorders." (PMID 36653874, 2023). "Although MALAT1 is not essential for development in a knockout mouse model under normal physiological conditions, MALAT1 has emerged as a player in IR-related metabolic disorders, especially in the liver." (PMID 40076814, 2025). "Recently, there has been tremendous focus on the possible role of MALAT1 in the pathogenesis of metabolic disorders and diabetic models." (PMID 36653874, 2023). "More recently, great attention has been paid to the probable role of two novel lncRNAs; metastasis-associated lung adenocarcinoma transcript 1 (MALAT1) and taurine upregulated gene 1 (TUG1) in the pathogenesis of metabolic disorders." (PMID 32368256, 2020). "Recent studies have begun to explore the role of MALAT1 in lipid metabolism, particularly within the liver, where it may influence the development and progression of metabolic diseases such as NAFLD." (PMID 40002783, 2025). "Thus, loss of Malat1 has no apparent significant consequence on age-associated metabolic diseases." (PMID 29746487, 2018). "Today, little is known about MALAT1 and TUG1 function and regulation in metabolic disorders." (PMID 32368256, 2020).
prostate (7 papers, 2016 to 2024). "Likewise, M2 macrophages released IL-8, which supported prostate carcinogenesis through the STAT3/metastasis-associated lung adenocarcinoma transcript 1 (MALAT1) pathway." (PMID 38745115, 2024). "We mainly intend to fathom out the functional role of MALAT1 in liver IR injury with utilization of a liver IR injury model and H/R model of liver immortalized cell lines THLE-2 and THLE-3." (PMID 36700468, 2022). "To conclude, MALAT1 targeted miR-150-5p/AZIN1 to accelerate liver IR injury, suggesting that MALAT1 might be a novel target for liver IR injury." (PMID 36700468, 2022). "More importantly, we conducted rescue experiments and verified that AZIN1 upregulation could neutralize the impacts of MALAT1 silence on the progression of liver IR injury." (PMID 36700468, 2022). "Furthermore, multivariable analysis confirmed MALAT1 to have independent prognostic significance in the basal-like lymph node negative patient subset (HR=2.64, 95%CI 1.35-5.16, p=0.005)." (PMID 27250026, 2016).
retinopathy (7 papers, 2020 to 2025). "By elucidating the association between retinopathy and MALAT1, this review hopes to contribute to ongoing research efforts in both fields and stimulate further investigations into their interplay." (PMID 40128064, 2025). "The understanding of the molecular mechanisms underlying the development and progression of retinopathy, along with the potential involvement of MALAT1, can provide valuable insights for the diagnosis and treatment of this condition." (PMID 40128064, 2025). "Understanding the roles of MALAT1 in retinopathy can shed light on the molecular mechanisms underlying the development and progression of these conditions, offering new possibilities for MALAT1 as a diagnostic and prognostic biomarker." (PMID 40128064, 2025). "Further investigations into the specific mechanisms underlying MALAT1’s involvement in retinopathy pathogenesis may provide valuable insights into the development of diagnostic and therapeutic approaches for managing retinal disorders." (PMID 40128064, 2025). "Long noncoding RNA (lncRNA) metastasis-associated lung adenocarcinoma transcript 1 (MALAT1) and retinopathy are 2 distinct yet interconnected areas of research in the field of ocular studies." (PMID 40128064, 2025). "Intravitreal injection of MALAT1 siRNA significantly reduced the degree of retinopathy compared to the OIR control group, leading to decreased protein and mRNA expression levels of CCN1, AKT, and VEGF." (PMID 40128064, 2025). "In this review, we aim to explore the characteristics and potential links between retinopathy and MALAT1." (PMID 40128064, 2025). "Additionally, the competing endogenous RNA (ceRNA) network involving MALAT1 indicates its potential relevance as a regulator in retinopathy." (PMID 40128064, 2025). "The emerging role of long noncoding RNA MALAT1 in retinopathy has attracted considerable attention." (PMID 40128064, 2025). "Additionally, we discuss the involvement of MALAT1 in retinopathy, examining its roles in pathogenesis and its potential as a therapeutic target." (PMID 40128064, 2025). "Similarly, MALAT1 increase in oxygen-induced retinopathy was counteracted by intravitreal injection of MALAT1-siRNA, which significantly improved the retinal phenotype." (PMID 33537317, 2020). "Although these results highlight MALAT1 silencing as a possible therapeutic strategy for different forms of retinopathy, the direct functional role of MALAT1 in PRs remains unclear, especially in light of the results linking its reduction to PR degeneration." (PMID 33537317, 2020). "Targeting MALAT1 could also present a novel therapeutic approach for managing retinopathy." (PMID 40128064, 2025). "In high glucose conditions a lncRNAMalat1 was found to be up-regulated in retinas while Malat1 lncRNA knockdown in STZ induced rats resulted impaired retinopathy suggesting that this lncRNA promotes retinopathy under diabetic condition." (PMID 32815547, 2020). "Nevertheless, the expression of MALAT1 and RNCR2 did not correlate with the severity of retinopathy and with the response to aflibercept therapy." (PMID 34638838, 2021).
hematological malignancies (6 papers, 2016 to 2024). "The upregulation of MALAT1 has been observed in many solid tumors and hematological malignancies, and high expression was found to be associated with the progression of disease, chemotherapy resistance, metastatic potential, and reduced patients’ survival, implying its pro-oncogenic role." (PMID 38255996, 2024). "Collectively, MALAT1 plays an important role in the pathogenesis of hematological malignancies and serves as a potential target for hematological malignancy diagnosis, prognosis, and treatment." (PMID 31480503, 2019). "Previous studies have reported high expression of lncRNA MALAT1 in solid tumors and hematologic malignancies and hinted to its role on transcription complexes." (PMID 27998273, 2016). "MALAT1 is known to be overexpressed in solid tumors and hematologic malignancies." (PMID 27998273, 2016). "In concert with MALAT1, also NEAT1 is emerging as a novel biomarker and crucial regulator in the pathogenesis of several human tumors although with distinct roles in solid tumors versus hematological malignancies." (PMID 33193626, 2020).
digestive system cancer (3 papers, 2016 to 2021). A primary or metastatic malignant neoplasm involving any part of the digestive system. "In addition, elevated lncRNA, metastasis associated lung adenocarcinoma transcript 1 expression was also a significant predictor for DFS in patients with digestive system cancers." (PMID 28410241, 2017).
colon polyps (2 papers, 2019 to 2023). "Collectively, these findings provide new insights into the function of MALAT1 in the intestine epithelium and its potential as a prognostic marker as well as a therapeutic target in intestinal diseases." (PMID 37325561, 2023).
digestive system tumors (2 papers, 2017 to 2022). "MALAT-1 is overexpressed in multiple types of human malignancies, such as the pulmonary cancers, digestive system tumors and genitourinary cancers, and so forth." (PMID 29254244, 2017).
hematological cancer (2 papers, 2016 to 2020). "MALAT1 is a well-studied lncRNA in several solid and hematological cancers." (PMID 32591022, 2020).
respiratory diseases (2 papers, 2017 to 2022). "The lncRNA MALAT1 is closely associated with the development and progression of respiratory diseases." (PMID 36419933, 2022). "The available evidence shows that MALAT1 plays an important role in the regulation of multiple respiratory diseases." (PMID 36419933, 2022). "Recent studies have shown that long non-coding RNA (lncRNA) MALAT1 is involved in various respiratory diseases." (PMID 36419933, 2022). "This review provides the first comprehensive analysis of the molecular mechanisms by which MALAT1 regulates the pathophysiology of various respiratory diseases and clarifies its relevance to complications of these diseases." (PMID 36419933, 2022). "Targeting the regulation MALAT1 could have important applications for the future treatment of respiratory diseases." (PMID 36419933, 2022). "MALAT1-mediated micro RNA regulatory networks in respiratory diseases." (PMID 36419933, 2022). "This review of the empirical and clinical evidence describes the potential mechanisms by which MALAT1 regulates respiratory disease and suggests that it could serve as a therapeutic target in the development of effective novel drug treatments for respiratory disease." (PMID 36419933, 2022). "A limitation of this review is that it only analyzed the relationship between MALAT1 and related respiratory diseases in terms of active or passive regulation, and did not investigate the role of MALAT1 in pathogenesis." (PMID 36419933, 2022).
central nervous system diseases (1 paper, 2022). "The regulatory mechanism of Malat1 helps to ascertain the therapeutic targets of central nervous system diseases and help to establish a complete treatment strategy." (PMID 35309141, 2022).
endocrine disorder (1 paper, 2024). "It was found that overexpression of MALAT1 seemed to play a protective role in reducing ovarian tissue damage and endocrine disorder in PCOS by regulating miR-302d-3p mediated leukemia inhibitory factor activity." (PMID 38424234, 2024).
muscular disorders (1 paper, 2019). "Thus, MALAT1 is associated with the regulation of myogenic differentiation and muscle regeneration, and the misregulation of MALAT1 is linked to muscular disorders." (PMID 30669611, 2019).
MALAT1 also shares sentences with these, for which no sentence is quoted: acute myocardial infarction (15 papers); endometrial stromal sarcoma (7); papillary thyroid carcinoma (6); pulmonary hypertension (6); cerebral infarction (4); inflammation (4); autism (3); B-cell lymphomas (3); chronic periodontitis (3); cystic tumors (3); neuropathy (3); retinopathy of prematurity (3); small cell lung carcinoma (3); anaplastic thyroid carcinoma (2); aortic valve disease (2); autoimmune thyroid disease (2); bone cancer (2); cervical (2); chondrosarcoma (2); chromophobe renal cell carcinoma (2); complication (2); esophageal adenocarcinoma (2); hypopharyngeal squamous cell carcinoma (2); intervertebral disc degeneration (2); intracranial aneurysm (2); leishmaniasis (2); lung adenoma (2); myositis (2); sarcoma (2); type 1 diabetes mellitus (2).
A further 106 diseases each share a sentence with MALAT1 in 2 papers or fewer.